NQO1 (NAD(P)H quinone dehydrogenase 1)
Diseases named in the same sentence as NQO1 in open-access papers (continued):
Sharing a sentence is not in itself a finding about the gene and the disease.
cancer (continued). "Thus, our data suggest that NQO1 stimulates CKS1 expression through upregulation of c-Fos, which, in turn, regulates cell cycle progression in cancer cells at the G2/M phase." (PMID 36793872, 2023). "In breast cancer model, miR-93 could decrease NRF2 expression at mRNA and protein levels to impair its downstream genes such as NQO1 and SOD3, thus playing a crucial role in regulating apoptosis and oxidative DNA damage in cancer cells." (PMID 35754474, 2022). "NQO1 is a homodimeric flavoprotein that contains a tightly bound FAD molecule per subunit, and it is involved in the two-electron reduction of substrates, including cancer prodrugs, vitamins and superoxide radicals." (PMID 35740007, 2022). "Furthermore, the activity of certain enzymes, such as NAD(P)H:quinone oxidoreductase-1 (NQO1), which are found in certain types of cancer microenvironments, can also be exploited." (PMID 36145608, 2022). "In this study, we show that combining PARPi with KP372-1 leads to synergistic antitumor effect with non-toxic doses of both drugs in NQO1 overexpressing cancer cells." (PMID 36203459, 2022). "Through NRF2 activation, DMF modulates the expression of a variety of anti-oxidant enzymes, including heme oxygenase 1 (HO-1) and NADPH dehydrogenase (quinone 1) (NQO1), thus dysregulating the intracellular radical oxygen species (ROS) level, whose fine balance is required for cancer cell survival." (PMID 35743211, 2022). "This would imply that NQO1 function and its ability to develop PPI might be affected in the global human population and, thus, not only related to confirmed cancer cell lines." (PMID 35629169, 2022). "Recently, KP372-1 was identified as a novel potential anticancer agent that targeted the redox enzyme, NAD(P)H:quinone oxidoreductase 1 (NQO1), to induce extensive reactive oxygen species (ROS) generation that amplified DNA damage, leading to cancer cell death." (PMID 36203459, 2022). "However, the situation is far from simple, and it has also been shown that NQO1 promotes AMPK activation and induces cancer cell death under oxygen–glucose deprivation." (PMID 35629169, 2022). "At the same time, NQO1 can regulate Akt and c-Myc through MAPK/ERK and PI3K/Akt signal pathways to regulate glucose and glutamine metabolism, which is closely related to the uncontrolled proliferation of cancer cells." (PMID 33424998, 2020). "The use of NQO1-bioactivatable drug (e.g., β-lap) with PARP inhibitors have been shown to significantly expand the clinical application of PARP inhibitors outside of BRCA1/2 mutant cancers for which the majority of PARP inhibitors are currently approved." (PMID 32295316, 2020). "This NQO1-dependent cycling of β-lap appears to be especially prominent in cancer cells, since such cells are reported to contain higher activities of NQO1 than non-cancerous cells, which supports the potential use of β-lap as an anti-cancer drug." (PMID 32789798, 2020). "The results showed that the expression of PRDX5 increased significantly in cancer samples than that of in the non-tumorous samples, and the same trend of Nrf2 and NQO1 protein levels compared to the adjacent normal ones." (PMID 31899687, 2020). "We summarize how aberrant alterations of PARG, NAMPT, NQO1, cMET and “BRCAness” genes that have been shown to affect PARP activity in cancers could serve as prognostic biomarkers for targeted therapy." (PMID 32295316, 2020). "For example, β-lapachone (β-lap) is a soluble ortho-naphthoquinone with potent anti-tumor and radiosensitizing activity only in the presence of high NQO1 activity, which is only noted in most malignant tumors but not in normal tissues." (PMID 32295316, 2020). "Of these patients, 15 (65%)/6 (26%)/2 (9%) showed a decrease/ an increase/no change respectively in NQO1 score in carcinomas." (PMID 31909204, 2020).
cancer (continued). "Further, a cohort of 150 retrospective patient samples, about half of the carcinoma samples (versus a quarter in benign/PIN groups) showed either negative or low NQO1 score." (PMID 31909204, 2020). "RES can inhibit activating enzymes such as CYP19 (aromatase) and CYP1B1 (a kind of cytochrome P450 enzyme), and induce the expression of detoxification enzyme of NQO1 (NAD(P)H:quinone oxidoreductase 1), thus blocking the formation of estrogen-DNA adducts to protect against estrogen-initiated cancer." (PMID 30687096, 2018). "NQO-1 and TrxR1 reduced in CGN pretreated cancer cells (A549) compared with the X-rays only." (PMID 28415625, 2017). "Data from studies using human cancer cells demonstrated that NQO1 distributes in the cytosol and nucleus, but not in the ER, mitochondria and Golgi." (PMID 27607467, 2016). "A further search of the oncomine database involving cancer cell line panels indicated that NQO1 expression in HL-60 cells is consistently low or absent." (PMID 27625902, 2015). "The results revealed that the relative mRNA expression level of NQO1 was significantly upregulated in cancers compared with adjacent non-tumor tissues." (PMID 24499631, 2014). "NAD(P)H: quinone oxidoreductase 1 (NQO1) mediated quinone reduction and subsequent UDP-glucuronosyltransferases (UGTs) catalyzed glucuronidation is the dominant metabolic pathway of tanshinone IIA (TSA), a promising anti-cancer agent." (PMID 24244442, 2013). "It has been shown that curcumin activated NRF2 in several cell types and exerted a cytoprotective effect through transcriptional induction of phase II enzymes, such as glutathione transferase, NQO1, HMOX-1, GCLC, and GCLM in certain human cancers, skin lesions, and neurodegenerative diseases." (PMID 23710286, 2013). "A number of the genes identified have been induced in normal human cells by BaP (e.g. CYP1B1 and NQO1) and this gives promise that the expression changes we are observing in these two cell systems are not likely to be artefacts of their cancer phenotype." (PMID 17042939, 2006). "Notably, our findings suggest that the enhancement of β‐Lap‐induced cell death by CGA is likely independent of NQO1 expression and ROS levels in cancer cells." (PMID 40014262, 2025). "By contrast to the NQO1 expression, immunohistochemical analysis of leukocyte common antigen CD45 revealed that CD45-positive immune cells resided at a higher level in the stroma of WT 3LL cancer tissues, indicating massive infiltrations of immune cells to WT 3LL tumor tissues." (PMID 41035689, 2025). "However, cells lacking both AIFM2 and NQO1 exhibit increased sensitivity compared to AIFM2 knockout U-2 OS cancer cells." (PMID 39534872, 2024). "We have previously reported that NQO1 levels are much higher in cardiovascular cells, including endothelial cells, smooth muscle, and cardiac H9c2 cells, than in other cell types, including bone marrow stromal cells, human SH-SY5Y neuronal cells, and human Caco-2 carcinomas." (PMID 38397822, 2024). "However, anticancer drugs activated by NRF2-induced enzymes such as NQO1 could be exploited in SOCS1-low/SOCS3-high HCC and other instances of NRF2-mediated cancer progression." (PMID 36765862, 2023). "Since most compounds that correlated strongly with DPIQ anti-cancer activity gave modest PCCs of 0.38–0.55 to NQO1 expression, except for benzo[e]perimidine 3a, which was noticeably stronger (PCC = 0.64), we searched for compounds with the strongest PCCs to NQO1 expression." (PMID 37446864, 2023). "ENO1, GAPDH, NQO1, PDIA4, and PDIA6 may serve as potential targets for cancer therapy." (PMID 37955007, 2023). "Hence, the classification effectiveness of ten biomarkers which was assessed overall was based on GPX2 and GPX3 as factors from the enriched pathways and CAV1, ENO1, NQO1, and P4HB as factors from functional classes to determine whether a patient had cancer." (PMID 37955007, 2023).
cancer (continued). "Averaged fluorescent signal intensities of NQO1, NRF1 and NRF2 from the whole cohort were plotted using Spearman’s correlation coefficient, which demonstrated no correlative relationship between NQO1 and NRF1 (r = 0.002) or NQO1 and NRF2 (r = −0.161) expression in cancer cells." (PMID 36359002, 2022). "This suggests that rucaparib + KP372-1 enhanced toxicity in NQO1 positive cancers may be relatively independent of oncogenic drivers involved." (PMID 36203459, 2022). "Previous reports have pointed out that NQO1 was significantly overexpressed in HCC tissue and involved in metabolic adaptation, which could affect glycolysis and glutaminolysis, resulting in uncontrolled rapid proliferation of cancer cells." (PMID 34939323, 2022). "To kill cancer cells, SDT shifts the intracellular environment toward pro-oxidant conditions, due to reactive oxygen species (ROS) accumulation; we, thus, investigated the mRNA expression of oxidative stress-related genes, namely, NFE2L2 and NQO1 in tumor tissue at 72 h after SDT (day 11)." (PMID 34681196, 2021). "Moreover, the data also suggest that Ref‐1 inhibitors are not detoxified by NQO1 since NQO1+ and NQO1− isogenic cancer cell lines show closely similar cytotoxicities to Ref‐1 inhibitors." (PMID 33274592, 2021). "This different and apparently contrasting behavior of β-lapachone seems to be attributable to the preferential accumulation of ROS species via this compound in NQO1-overexpressing cancers, but not in normal cells (that are protected by low NQO1 expression and by high catalase levels)." (PMID 34068917, 2021). "Moreover, NQO1-targeted PDT combined with other strategies—such as immunotherapy, gas therapy, and starvation therapy—can stimulate immune reaction, augment the therapeutic effect of ROS, and deteriorate cancer cells, respectively." (PMID 34947831, 2021). "Since NQO1 and GSTP1 are phase-II detoxification enzymes that reduce quinones directly to hydroquinones, eliminating the formation of ROS produced by redox cycling, the combination of inhibition of NQO1 and GSTP1 may offer a potential solution for cancer therapy." (PMID 33087132, 2020). "Many studies have reported that β‐lap induces an undesired futile redox cycle, which is dependent on NQO1, resulting in an imbalance of redox cycle and induces oxidative stress to DNA by intracellular ROS production, which sequentially leads to PARP activation in cancer cells." (PMID 31353811, 2019). "Despite the great implication of NQO1 as a biomarker for early diagnosis of cancer, none of the reported fluorescent probes have been evaluated for the non-invasive diagnosis of cancer in orthoptic cancer xenograft models." (PMID 31189950, 2019). "Thus, the co-administration of β-lapachone and PARP inhibitors to cancer cells generates considerable amount of hydrogen peroxide without affecting the NAD pools that constantly refuel NQO1 redox cycling and induce massive DNA damage." (PMID 30631755, 2018). "In addition, NQO1 activated by bL accelerates the conversion of NADH to NAD+, and increased cellular NAD+ levels may affect cancer cell proliferation." (PMID 30513573, 2018).
cancer (continued). "By this mechanistic link, our study provides new insights to better understanding the role of tryptophan depletion and de-novo NAD+ synthesis in cancer biology and therapy, and may pave the way to new therapeutic options in NSCLC via dual targeting NQO1 and the components in de-novo NAD+ synthesis." (PMID 27566573, 2016). "In response to NQO1 activation-triggered oxidative stress, the adaptively activated salvage NAD+ synthesis is insufficient to compensate for the PARP-1 activation induced rapid depletion of NAD+, rendering the cancer cells more reliant on the de-novo NAD+ synthesis from tryptophan." (PMID 27566573, 2016). "NQO1 overexpression induced tumor cell proliferation via the up-regulation of cyclins and was accompanied by an increase in other antioxidant enzymes, such as HMOX-1 and GST, providing tumors with increased protection against cytotoxic agents allowing for rapid cancer progression." (PMID 28983331, 2015). "Prior data from our laboratory demonstrated that a 30–60 min exposure to ß-lap at 4 μM, but not 2.5 μM, could kill NQO1+-overexpressing cancer cells, including PDA MiaPaca2 cells." (PMID 26602448, 2015). "Additionally, while NQO1:CAT was not directly measured, inhibition of catalase and GSH did not lead to sensitization of KEAP1-mutated NSCLC during β-lapachone treatment, while inhibition of TXNRD and SOD1 sensitized cancers." (PMID 36978989, 2023). "Conversely, neither the PAR nor γ-H2AX protein was noted in the A549 NQO1-knockout cells after IP-DNQ treatment, indicating that IP-DNQ kills cancer cells in an NQO1-dependent manner." (PMID 38136388, 2023). "The patient characteristics, such as cancer grade, inflammation, residual tumor, and AFP level, did not significantly differ between the high- and low-NQO1-expression groups, except for vascular invasion." (PMID 37695786, 2023). "NQO1 expression was not correlated to paired NRF1 or NRF2 expression in cancer, immune or stroma cells, contrary to studies proposing NRF1- or NRF2-directed adaptive response upon NQO1 transcription in mice and human keratinocytes." (PMID 36359002, 2022). "In all cancer cell lines, the more harsh condition of NC3 did not significantly affect the NQO1 cytoplasmic levels which remained close to the NQO1 control levels (NC1)." (PMID 31470592, 2019). "Genes involved in the glutamine-dependent transamination pathway (GLS1, GOT1/2, ME1) and NQO1, but not GLUD1, are highly expressed in PDA relative to other cancers." (PMID 26462257, 2015). "Co-treatment with either 108 or 109 and β-lapachone, known to excessively generate ROS in living cells upon reduction to 111 by NQO1,200 induced efficient degradation of the respective POI in cancer cells, while negligible effects were observed in noncancerous cells." (PMID 35983982, 2022).
tumor (325 papers, 1992 to 2026). "Although the fraction of NQO1 positive ccRCC was small (36 of 469 tumours), we found significant association of NQO1 expression with high ISUP grade (p = .0045) and worse patient survival (p = .003)." (PMID 39707614, 2025). "Bulk RNA‐seq of paired tumor/normal tissue (n = 17) and external datasets confirmed significant NQO1 overexpression in tumor tissue, associating with poor prognosis." (PMID 41028931, 2025). "One case of HGIN was found to have 2 tumor-associated genes with germline mutations, including NQO1 and BRAT1." (PMID 39792765, 2025). "Among 10 patients with HGIN and early-stage GCA, among the tumor-associated genes, 7 cases were found to have germline mutations in the NAD(P)H:quinone oxidoreductase 1 (NQO1)." (PMID 39792765, 2025). "Lastly, NQO1-directed therapeutics will increase a tumor cell’s susceptibility to clinical chemotherapeutics." (PMID 36980879, 2023). "In view of this, we decided to analyze the correlation between the NQO1 mRNA expression levels, the tumor mutation burden, and microsatellite instability." (PMID 37583897, 2023). "SET, which is reversible by oxygen and mediated by NADPH-cytochrome (P450) reductase, is associated with tumour hypoxia, and is prevented by the NQO1-mediated two-electron reduction." (PMID 37446864, 2023). "High NQO1 protein expression in tumor cells was associated across NRF1low and NRF2low regions, whereas low NQO1 expression is demonstrated in tumor cells detailing NRF1high and NRF2high expression." (PMID 36359002, 2022). "Altering NQO1 expression potently triggers innate sensing within the tumor microenvironment, causing NQO1-activated β-lapachone to overcome immunotherapy resistance." (PMID 34437536, 2021). "While these findings indicate that NQO1 is positively associated with tumor growth and malignant progression, NQO1 is also protective against carcinogens, essential for anti-ROS defense, quinone detoxification, and metabolic stress." (PMID 31909204, 2020). "Elevated NRF2 abundance and expression of the NRF2-target genes GCLC and NQO1 have been found in both ESCC tumours and cell lines, and are associated with poor patient survival." (PMID 33276631, 2020). "To investigate the putative mechanism underlying NQO1-induced tumor suppressive effect, we determined the cellular ROS level after the overexpression or knockdown of NQO1." (PMID 31886179, 2019). "We discovered that after activation by NQO1, β-lap caused tumor-selective cell death and induced innate sensing for adaptive antitumor immunity." (PMID 31324798, 2019). "NQO1 is expressed in many human solid tumors at levels of 200-fold above that in normal tissue and its elevated activity has been closely associated with tumor progression, aggressiveness, resistance to chemotherapy, and poor prognosis." (PMID 30487423, 2018). "All efficacy parameters (response, PFS, time on study treatment) had either a statistically significant (or trend towards) association with tumour NQO1 expression." (PMID 30318513, 2018). "ARQ 761 is a β-lapachone (β-lap) analogue that exploits the unique elevation of NQO1 found in solid tumours to cause tumour-specific cell death." (PMID 30318513, 2018). "After analysis of 20 patients with evaluable response and available NQO1 expression level, we observed a near significant association (P = 0.06) between tumour NQO1 expression (H-score ≥ 200) and response." (PMID 30318513, 2018). "Preclinical studies therefore demonstrated that EO9 has the ability to target both the aerobic fraction of NQO1-rich tumours (where selectivity is determined by elevated levels of NQO1 in tumours) and the hypoxic fraction of NQO1-deficient tumours." (PMID 26811177, 2016).